ROCK1 (Rho associated coiled-coil containing protein kinase 1)
Diseases named in the same sentence as ROCK1 in open-access papers (continued):
Sharing a sentence is not in itself a finding about the gene and the disease.
Sepsis (9 papers, 2021 to 2024). Sepsis is defined as life-threatening organ dysfunction caused by a dysregulated host response to infection. "The long non-coding RNA NEAT1 mediates LPS-induced pyroptosis of BEAS-2B cells through the miR-26a-5p/Rho-associated coiled-coil containing protein kinase 1 (ROCK1) axis, contributing to the pathogenesis of sepsis-associated ALI." (PMID 39911675, 2024). "miR-539-5p reduced ALI caused by sepsis via targeting ROCK1 and showed the inhibitory effect of apoptosis and inflammation in MPVECs." (PMID 33954185, 2021). "Moreover, miR-539-5p alleviates sepsis-induced acute lung injury (ALI) via suppressing its downstream target Rho-associated kinase 1 (ROCK1), suggesting a therapeutic potential of miR-539-5p for the management of sepsis-induced ALI." (PMID 34757596, 2022). "Another experiment in an animal model of sepsis-induced acute lung injury demonstrated the effect of miR-539-5p in alleviation of lung injury through modulation of expression of ROCK1." (PMID 36177350, 2022). "Similarly, over-expression of miR-539-5p alleviates sepsis-induced acute lung injury via suppressing its downstream target ROCK1." (PMID 34757596, 2022). "Increased serum MSN contributes to the sepsis-related endothelium damages by activating the Rock1/MLC and NF-κB signaling and may be a potential biomarker for evaluating the severity of sepsis." (PMID 33628853, 2021). "Not all targets in the sepsis pathway are related to glycocalyx, and there are 6 targets (SI, ROCK1, TLR4, VEGFA, HPSE, and LGALS3) of active ingredients not only related to glycocalyx, but also involved in the sepsis pathway." (PMID 36062176, 2022).
Alzheimer disease (7 papers, 2012 to 2025). A progressive, neurodegenerative disease characterized by loss of function and death of nerve cells in several areas of the brain leading to loss of cognitive function such as memory and language. "GSK-3β, IKK-β, and ROCK-1 kinases are implicated in the pathomechanism of Alzheimer’s disease due to their involvement in the misfolding and accumulation of amyloid β (Aβ) and tau proteins, as well as inflammatory processes." (PMID 38893493, 2024). "Alzheimer’s disease (AD) is the most prevalent form of late-life dementia in the population, characterized by amyloid plaque formation and increased tau deposition, which is modulated by Rho-associated coiled-coil kinase 1 (ROCK1)." (PMID 27853422, 2016). "Here, we combined structural elements found in inhibitors of three kinases—GSK-3β, IKK-β, and ROCK-1—to develop multifunctional ligands targeting processes involved in the progression of Alzheimer’s disease." (PMID 38893493, 2024). "ROCK1 is activated in Alzheimer’s disease, and reduction of ROCK1 protects against AD by depleting amyloid-β levels in the brain." (PMID 34836168, 2021). "In particular, it is highly associated with both viral infection and prion diseases in the brain.miR-146a has been shown to suppress rho-associated, coiled-coil-containing protein kinase 1 (ROCK1), which results in hyperphosphorylation of Tau in association with Alzheimer's disease." (PMID 36788995, 2023). "Some of the other up-regulated transcripts in the VMB include members of axon guidance signaling (Rock1, Adam22), zinc finger proteins (Eif2c3 and novel KRAB box and zinc finger, C2H2 type domain containing protein) and one of the candidate genes for late onset Alzheimer's Disease (Plce1)." (PMID 22563483, 2012).
asthma (7 papers, 2009 to 2025). "RhoA/ROCK1 signal pathway has been reported to serve as a proximal downstream effector of numerous GPCRs, and plays an important role in the pathophysiology of asthma, including airway smooth muscle contraction, AHR, and airway remodeling." (PMID 36803977, 2023). "Mechanistically, the effects that DC260126 alleviated obese asthma was correlated with the down-regulation of GTP-RhoA and Rho-associated coiled-coil-forming protein kinase 1 (ROCK1)." (PMID 36803977, 2023). "In the mouse model of asthma, Rock1+/− and Rock2+/− mice showed attenuated mast cell degranulation and reduced number of eosinophils, but both developed unaffected lung inflammation." (PMID 32178482, 2020). "We then explored whether the RhoA/ROCK1 signaling pathway was involved in GPR40-regulated asthma in obese mice." (PMID 36803977, 2023). "RhoA/ROCK1 pathway has been reported to link closely with AHR in asthma." (PMID 36803977, 2023). "However, whether GRP40 regulates AHR in obese asthma through RhoA/ROCK1 signal pathway remains elusive." (PMID 36803977, 2023). "Several studies have revealed a diverse range of functions of ROCK1 and 2 in the context of lung diseases and ROCK inhibitors have potential therapeutic applicability in lung diseases such as asthma, COPD and pulmonary fibrosis." (PMID 33551810, 2020). "Interestingly, although immunohistochemical analysis revealed no changes in MYPT1 expression or its phosphorylated forms in the bronchial smooth muscle of guinea pig asthma model, both RG1 and ROCK2—but not ROCK1—showed significantly increased expression levels." (PMID 41463119, 2025).
liver cancer (7 papers, 2021 to 2024). An epithelial or non-epithelial malignant neoplasm that arises from the liver. "LINC00491, miR-324-5p and rho-associated kinase 1 (ROCK1) expression in liver cancer patients and cells were detected by quantitative reverse transcription-polymerase chain reaction and Western blot." (PMID 34876144, 2021). "MiR-199a/b-5p was reported to inhibit the activation of the ROCK1/MLC and PI3K/Akt signaling pathways by negatively regulating ROCK1 expression, leading to the inhibition of liver cancer metastasis." (PMID 33959508, 2021). "miR-324-5p or si-ROCK1 counteracted the promotion of LINC00491 on liver cancer cells malignant phenotype." (PMID 34876144, 2021). "qRT-PCR presented that, ROCK1 was highly expressed in the tumor tissues of liver cancer cases than that in normal tissues (P < 0.0001)." (PMID 34876144, 2021). "Taken together, ROCK1 knockdown reversed the promotion of LINC00491 on liver cancer cells malignant phenotype." (PMID 34876144, 2021). "Taken together, the promotion effects of LINC00491 on liver cancer progression might be through enhancing ROCK1 expression via directly reducing miR-324-5p." (PMID 34876144, 2021). "LINC00491 facilitated liver cancer progression by sponging miR-324-5p/ROCK1." (PMID 34876144, 2021). "In this research, it was shown that ROCK1 was highly expressed in liver cancer tissues." (PMID 34876144, 2021). "Moreover, ROCK1 knockdown counteracted the effects of LINC00491 on the biological behaviors of liver cancer cells." (PMID 34876144, 2021). "Overall, this study indicated that LINC00491 might play a promotion role in the development and metastasis of liver cancer through miR-324-5p/ROCK1." (PMID 34876144, 2021). "Their insights into the mechanism revealed FOXM1’s role in promoting liver cancer cell invasion and metastasis by upregulating MMP-7, RhoC, and ROCK1, with HBx further amplifying FOXM1 expression through the ERK/CREB pathway." (PMID 37817774, 2023). "Comparing normal liver tissue samples (225 patients) and liver hepatocellular carcinoma (LIHC) samples (371 patients), the expression of the genes: RhoA, Rac1, LIMK1, LIMK2, ROCK1, ROCK2, MLCK2, and PAK4 is upregulated in liver cancer." (PMID 35241781, 2022). "In addition, miR-324-5p not only counteracted the regulation of LINC00491 on ROCK1, but also counteracted the effects of LINC00491 on the proliferation, apoptosis, migration and invasion of liver cancer cells." (PMID 34876144, 2021).
liver fibrosis (7 papers, 2019 to 2024). "In conclusion, the NOX4/ROS and RhoA/ROCK1 signalling pathways are closely linked to the development of liver fibrosis." (PMID 32496208, 2020). "Here we show that therapeutic administration of GV101, a selective ROCK2 inhibitor with more than 1000-fold selectivity over ROCK1, attenuates established liver fibrosis induced by thioacetamide (TAA) in combination with high-fat diet in mice." (PMID 37980369, 2023). "We have demonstrated that Rac1 is involved in NOX activation and that NOX4/ROS can also induce HSC activation by activating the RhoA/ROCK1 signaling pathway, thereby promoting liver fibrosis." (PMID 32083022, 2020). "Compared to that in the CCl4 group, the mRNA level of NOX4 in the RhoAi group was decreased to a certain degree, but this difference was not statistically significant, indicating that NOX4/ROS is the upstream signalling pathway of RhoA/ROCK1 in liver fibrosis." (PMID 32496208, 2020). "The present study investigated the interaction between NOX4/ROS and RhoA/ROCK1 in hepatic fibrosis, the direct binding of NOX4 and RhoA, and the specific antifibrosis molecular targets of UA." (PMID 31130857, 2019). "In conclusion, our results indicate that NOX4/ROS and RhoA/ROCK1, which may interact, play an important role in the development of liver fibrosis." (PMID 32496208, 2020). "We investigated the interaction between NOX4/ROS and RhoA/ROCK1 during liver fibrosis and whether these molecules are targets for the anti-fibrotic effects of UA." (PMID 32496208, 2020). "We aimed to determine the relationship between NOX4/ROS and RhoA/ROCK1 in liver fibrosis." (PMID 32496208, 2020). "This suggests that NOX4/ROS may be the upstream signalling pathway of RhoA/ROCK1 in liver fibrosis." (PMID 32496208, 2020). "In conclusion, these results suggest that FA combined with BMSC treatment can induce greater release of miR-19b-3p, which inhibits the activation of HSCs by suppressing the RhoA/ROCK1/SRF and RhoA/ROCK1/LIMK1 pathways, contributing to alleviation of liver fibrosis." (PMID 35721175, 2022). "UA can reverse liver fibrosis by inhibiting the NOX4/ROS and RhoA/ROCK1 signalling pathways, which may interact with each other." (PMID 32496208, 2020). "The interaction between NOX4/ROS and RhoA/ROCK1 in liver fibrosis is not yet clear." (PMID 32496208, 2020).
Myocardial fibrosis (7 papers, 2013 to 2024). "MT improved cardiac function and myocardial fibrosis in rats by inhibiting the expression of the RhoA/ROCK1 signaling pathway." (PMID 39041001, 2024). "Uncaria rhynchophylla (UR) is known to have significant hypotensive effects and can attenuate Ang II-induced myocardial fibrosis by inhibiting the RhoA/ROCK1 signaling pathway." (PMID 36387359, 2022). "Further, perivascular and myocardial fibrosis, arterial intimal thickening were assessed by histology, and capillary density, nitrotyrosine and ROCK1/2 expressions were evaluated by immunohistochemical staining." (PMID 24059472, 2013). "Matrine could inhibit the activation of RhoA/Rock1 signaling pathway, reduce myocardial fibrosis, prevent ventricular remodeling, and improve cardiac function in rats with heart failure." (PMID 35433636, 2022). "The RhoA/ROCK-1 pathway plays a significant role in myocardial fibrosis." (PMID 27611832, 2016).
osteoporosis (7 papers, 2009 to 2024). A condition of reduced bone mass, with decreased cortical thickness and a decrease in the number and size of the trabeculae of cancellous bone (but normal chemical composition), resulting in increased fracture incidence. "Further bioinformatics analysis and experiments had found that circ_0006859 can upregulate ROCK1, inhibit bone formation, and promote fat formation by sponge forming miR-431-5p, and finally leading to the occurrence of osteoporosis." (PMID 38798702, 2024). "Conversely, by increasing ROCK1 expression, strontium ranelate (SrR, an anti-osteoporosis drug) promotes the osteogenesis of ovariectomy rat bone marrow mesenchymal stem cells (OVX-rBMSCs) and cell viability of primary osteoblasts." (PMID 37683138, 2023). "This is the first study demonstrating the important role of the hsa_circ_0006859/miR-431-5p/ROCK1 axis during osteoporosis." (PMID 33648601, 2021). "The elevated level of ROCK1 is determined to be involved in the anti-osteoporosis effect of Strontium ranelate (SrR)." (PMID 34617877, 2021). "In light of the previous evidence, we deduced that ROCK1 might be involved in the role of ROR/miR-145-5p in osteoporosis." (PMID 34617877, 2021). "ROCK1 might be involved in the role of ROR/miR-145-5p in osteoporosis." (PMID 34617877, 2021).
renal cell carcinoma (7 papers, 2011 to 2023). "miR-584 was shown to decrease cell motility through the inhibition of Rho-associated coiled-coil-containing protein kinase 1 (ROCK-1) in renal cell carcinoma (RCC) cell lines, and the expression of miR-584 was inversely correlated with that of ROCK-1 in RCC tissues." (PMID 26563372, 2016). "There is a study showing that in renal cell carcinoma progression, miR-126 attenuates the ability of renal cell carcinoma cells to invade and metastasize by targeted inhibition of Rock1 expression." (PMID 34500436, 2021). "However, previous studies only focus on renal cell carcinoma (RCC), and multiple miRNAs (such as miR-126, miR-199a, and miR-584) impaired the progression of RCC targeting ROCK1." (PMID 37683138, 2023). "Therefore, we observed that miR-584 decreased cell motility through inhibition of ROCK-1 in RCC cell lines and the expression of miR-584 was inversely correlated with that of ROCK-1 in ccRCC (clear cell renal cell carcinoma) tissues." (PMID 21119662, 2011).
retinoblastoma (7 papers, 2014 to 2025). A malignant tumor that originates in the nuclear layer of the retina. "Previously reported that retinoblastoma invasion and proliferation can be inhibited by the miR-148b-3p/ROCK1 axis via the role of the lncRNA NEAT1." (PMID 40165339, 2025). "Previously, miR-448 was reported to directly target ROCK1, thus suppressing the progression of retinoblastoma." (PMID 34055841, 2021). "MiR-204-5p restrained the malignant progression of retinoblastoma by regulating ROCK1 expression." (PMID 36550514, 2022).
Stroke (7 papers, 2015 to 2025). Sudden impairment of blood flow to a part of the brain due to occlusion or rupture of an artery to the brain. "Both miR-139 and miR-335 are closely associated with stroke-induced angiogenesis via ROCK1 and ROCK2 signalling (both ROCK1 and ROCK2 are VEGF signalling regulators)." (PMID 27275837, 2016). "Among the top 18 miRNAs of which the predictive binding scores were higher than 0.9, miR-335-5p and miR-1972 stroke our sight because DANCR and ROCK1 shared the similar miRNA response elements (MREs) for miR-335-5p and miR-1972 (predicted by DIANA-LncBase and TargetScan)." (PMID 29753317, 2018). "Lastly, ROCK1, while not directly involved in oxidative stress response, acts as a negative regulator of VEGF-induced angiogenic endothelial cell activation, which can have implications in vascular health and stroke risk." (PMID 39337941, 2024). "Interestingly, despite no change in protein levels of ROCK1 and ROCK2, overall ROCK activity appeared elevated in intact WT males 48 h post-stroke." (PMID 38164600, 2024).
type 2 diabetes (7 papers, 2018 to 2026). "However, the precise mechanisms by which ROCK1 affects DCM caused by type II diabetes is still unclear." (PMID 35865967, 2022). "We have recently reported that type 2 diabetes promotes centrosome amplification via enhancing the expression, biding, and centrosome translocation of rho‐associated coiled‐coil containing protein kinase 1 (ROCK1)/14‐3‐3σ complex in HCT116 cells." (PMID 30478982, 2019). "Fasudil reverses this process by inhibiting the expression and activity of ROCK1, thereby exerting a protective effect against type 2 diabetes-induced cardiac dysfunction." (PMID 35865967, 2022). "The results suggest that type 2 diabetes promotes centrosome amplification via ROCK1 and 14‐3‐3σ, with high glucose, insulin, and palmitic acid as the triggers." (PMID 30478982, 2019). "Similarly, inhibition of ROCK1/2 activity in type 2 diabetes-induced pluripotent stem cell-derived hepatocytes restored aspects of insulin signaling." (PMID 41535231, 2026). "In vivo, we found that type 2 diabetes enhanced the expression and activation of ROCK1 (p < 0.05)." (PMID 35865967, 2022). "Here, we provided evidence that HG could upregulate the ROCK1 protein level in cardiomyocytes, and treatment with Fasudil significantly reduced the expression and activation of ROCK1 induced by type II diabetes." (PMID 35865967, 2022). "In the type 2 diabetic GK rat model, ROCK1 is activated at the membrane of smooth muscle cells and endothelial cells in areas of constricted capillaries and vessels and is reported to contribute to lumen closure through vascular constriction and endothelium blebs." (PMID 34452066, 2021). "In this study we identified a progressive and ubiquitous over-expression of ROCK1 throughout the Type 2 diabetic heart that may explain the augmented vasodilatory (and reperfusion) response to fasudil in the 24-week-old db/db mice." (PMID 29928236, 2018). "In our recent report, we showed that the protein levels of ROCK1 and 14‐3‐3σ as well as centrosome amplification were all increased in PBMC from the patients with type 2 diabetes." (PMID 30478982, 2019).
acute myeloid leukemia (6 papers, 2016 to 2025). Acute myeloid leukemia (AML) is a group of neoplasms arising from precursor cells committed to the myeloid cell-line differentiation. "Expression levels of ROCK1-targeting miR-592 were reported to be decreased in clinical samples from patients with acute myeloid leukemia (AML) as well as AML cell lines." (PMID 36177350, 2022). "GSK269962A (GSK, Marietta, PA, USA), a selective ROCK1 inhibitor, exhibited anti-leukemic effects in murine models of acute myeloid leukemia by inducing apoptosis and inhibiting the ROCK1/c-Raf/ERK signaling axis, thereby reducing leukemic infiltration and prolonging survival." (PMID 41377066, 2025). "In acute myeloid leukemia (AML), ROCK1 depletion by genetic knockout or ROCK inhibition with H-1152, Y27632, or fasudil reduced the survival of malignant cells bearing oncogenic form of KIT, FLT3, and BCR-ABL through suppressing MLC phosphorylation." (PMID 26725045, 2016). "In acute myeloid leukemia (AML), AML-derived mesenchymal stem cells (AML-MSCs) deliver METTL14 to leukemia cells via exosomes, where it stabilizes ROCK1 expression through the m6A-IGF2BP3 axis, thereby mediating radioresistance." (PMID 40823093, 2025).
colitis (6 papers, 2021 to 2025). Inflammation of the colon. "Treating the colitis mice with the ginsenoside Rg1 and Rock1 inhibitor Y27632 upregulated the peripheral blood CD11b+F4/80+CD163+ M2 macrophages." (PMID 36072401, 2022). "SSP significantly improved the clinical symptoms of colitis in rats and reduced the expression of p-RhoA, ROCK1, PI3K, and Akt in the colon mucosa, while it increased the expression of p-Rac and related proteins (Claudin-5, JAM1, VE-cadherin, and Connexin 43)." (PMID 34925530, 2021). "However, continuous treatment with NaHS from day one after colitis decreased the expression of RhoA, ROCK1, and ROCK2 proteins in CSE KO and WT mice." (PMID 36189321, 2022). "The expression of RhoA, ROCK1 and ROCK2 was significantly increased in colitis." (PMID 36189321, 2022). "Therefore, it is not surprising that colitis-induced RhoA, ROCK1, and ROCK2 expression levels were even higher in CSE KO mice than in WT mice." (PMID 36189321, 2022).
endometrial cancer (6 papers, 2020 to 2025). Primary or metastatic malignant neoplasm involving the endometrium (mucous membrane that lines the endometrial cavity). "Furthermore, TRPV4 regulates the cytoskeleton of endometrial cancer cells through the RhoA/ROCK1 pathway, thereby promoting metastasis." (PMID 39895789, 2025). "And through the correlation analysis of the expressions of ECT2 and RhoA, ROCK1, and ROCK2 in endometrial cancer samples in TCGA database, it was found that the expression of ECT2 was significantly positively correlated with RHOA, ROCK1, and ROCK2." (PMID 40655948, 2025). "Moreover, RhoA/ROCK1/LIMK/Cofilin signaling pathway has been reported to induce motility-related changes in the actin cytoskeleton and cell migration of endometrial cancer." (PMID 35379791, 2022).